TNF (tumor necrosis factor)
Diseases named in the same sentence as TNF in open-access papers (continued):
Sharing a sentence is not in itself a finding about the gene and the disease.
infection (continued). "At 6 h post-infection, except GM-CSF and IL-2 were significantly higher in the ESRD group than in the control group, the levels of IL-8, IL-10, IL-12p40, TNF-α, MCP-1, and MIP-1b were found to be lower in the ESRD group." (PMID 31875015, 2019). "In previous studies we observed that phagocytosing PBMO and CBMO express similar levels cell associated TNF whereas CBMO secrete much lower levels of soluble TNF than PBMO 24 h and 48 h post-infection (p.i.)." (PMID 30897723, 2019). "Infection with MTB or M. avium leads to production of active TGF-β, which blocks the ability of either IFN-γ or TNF-α to inhibit intracellular replication." (PMID 30818784, 2019). "In contrast, infection of SK-N-SH with WNV reportedly results in a sharp increase of key pro-inflammatory cytokines (e.g., IL-1β, IL-6, IL-8, and TNF-α) at day 2 p.i., which coincides with peak virus replication." (PMID 31699097, 2019). "The inflammatory kinetics of serum in mice at 1, 3, 7 and 11 days after infection by SL1344, CVCC541, and CMCC50115 showed that SL1344 induced significantly high levels of IL-1β, IL-6 and TNFα at 1 and 3 days." (PMID 30898022, 2019). "In a multicenter, prospective study conducted in Italy for 10 years, the anti-TNF agents infliximab and adalimumab were administered to 2,475 and 604 IBD patients, respectively, to compare the occurrence of infections, malignant neoplasms, and death." (PMID 31025187, 2019). "Th1mediated cytokines such as interleukin (IL) 12, tumor necrosis factor alpha(TNF-α) and interferon gamma (IFN-γ) have been shown to be critical for thecontrol of this infection." (PMID 31130996, 2019). "We observed that the infection induced upregulation in the mRNA expression of liver IL-1β, IL-6, IFN-γ, and TNF-α, while treatment of P. chabaudi-infected mice with IE resulted in a significant downregulation in the expression levels of these cytokines." (PMID 30838089, 2019). "Our data showed that PRV AH02LA infection upregulated specific cytokines expression, such as IL-1β, IFN-γ, and TNF-α in the ileum and IL-1β, IL-10, IFN-γ, and TNF-α in the colon." (PMID 31195631, 2019). "Going well along with an improved response to infection, SIRT3/5−/− mice had significantly higher blood concentrations of TNF at day 1 (P = 0.001), TNF and IL-1β at day 2 (P = 0.004 and 0.03) and KC/CXCL1 at day 3 (P = 0.05)." (PMID 31632409, 2019). "Infection of mice with S. aureus-induced an early inflammatory cytokine response with high levels of IL-1α, IL-1β, IFN-β, TNF-α, IL-6, IL-12p70, IL-27, and IFN-γ in the spleen detected for up to 12 h pi compared to PBS-treated mice." (PMID 31134074, 2019). "Compared with the mice in the CTRL group, those in the CR-infection and QUE groups showed significantly elevated IL-10, IL-17, IL-6, and TNF-α levels (all p < 0.05)." (PMID 31156598, 2019). "HSV-2-infected DCs secrete TNF-α, which through signaling processes mediated by TNFR1 and TNFR2 has been reported to induce increased expression of CCR5 in DCs, enabling subsequent infection of these cells with HIV-1." (PMID 31114761, 2019). "FasL and TNFα were most robustly induced, but TRAIL was only mildly induced in response to infection." (PMID 30862035, 2019). "SCs responded to infection with increased expression of mRNAs for IFNβ, IFNλ, IFIT-1, Mx1, NLRP3, IL-23A, IL-6 and TNFα." (PMID 31289325, 2019). "Downstream effectors of TLR signaling include a variety of pro-inflammatory cytokines and chemokines such as IFN-γ, IL-6, TNF, IL-12, IFN-1, MCP-1, and IL-8 that take part in the amplification of anti-parasite responses during acute blood-stage infection." (PMID 31417551, 2019). "In contrast, both routes of infection induced populations of CD4+ T cells producing IFN-γ, IL-2, and TNF." (PMID 31356170, 2019). "Similar to infection in BMDMs, lungs from coinfected WT mice showed increased production of IL-1β, TNF-α, and IL-6 compared to PR8 or S. p. single infection of WT mice." (PMID 30794604, 2019).
infection (continued). "High levels of TNF-α, IL-1β, and CXCL10 are present in amniotic fluid from pregnancies complicated by infection compared to uninfected controls." (PMID 31133875, 2019). "A substantial decrease in IL-6, IL-9, IL-12p40/p70, IL-13, IL-17, IFN-γ, CCL5, SCF, TNF-α, TPO, and vascular endothelial growth factor (VEGF) was observed across days 4 through 7 of NTHi infection." (PMID 31548315, 2019). "The expression of TNF-α, IL-12p70, and IL-10 was induced by MAH-infected DCs exposed to LPS in the same manner as LPS-alone treatment in TLR2−/− and as MAH-alone infection in TLR4−/−." (PMID 31440223, 2019). "Cytokines GM-CSF, GRO-α, I-309, IL-1β, IL-6, MCP-1, MCP-2, TNF-α, thrombopoietin, BLC, Flt-3 ligand, HGF, IP-10, MIF, and MIP-3α were elevated by ≥1.5 fold relative to mock infection in both independent biological replicates of the cytokine array." (PMID 31536604, 2019). "During Mtb infection, we observed the largest shift in glycolysis at D35 post-infection, which also corresponded with the highest levels of IFN-γ and TNF-α production." (PMID 31825836, 2019). "Interferon-gamma (IFN-γ), tumor necrosis factor-alpha (TNF-α), and interleukins (e.g., IL-6, IL-10) are cell-signaling cytokines that activate and drive differentiation of immune cells upon infection." (PMID 31394828, 2019). "TSVE moderately up-regulated the mRNA level of IL-6, IL-8, TNF-α, IFN-β, CXCL9 and MX1 over the infection time." (PMID 30866776, 2019). "In vitro infection using human THP-1 cells (leukemia cell line) indicated that E. chaffeensis induces upregulation of IL-8, IL-1β, and TNF-α mRNAs as well as the extracellular regulated kinase 2 (ERK2) activation." (PMID 31134081, 2019). "Levels of TNF-α and CCL2 were significantly elevated from pre-clinical to early-stage infection, and IL-6, IL-12b, CCL3, CCL12, and ISG15 levels were significantly elevated from pre-clinical to late-stage infection." (PMID 31790513, 2019). "Infection with the SV12 strain induced a stronger immune response as the gene transcript levels of IL-17, TNFα and IFNγ were more pronouncedly up-regulated compared to the C. jejuni strain 81–176." (PMID 30922352, 2019). "The ELLAITTVVGNQ and the FRYPRPKHCCHTQVA peptides before infection, and both together with the KFWCLVIDALKRIG peptide after infection determined the most potent IFN-γ and TNF-α/IL-10 ratios in mice vaccinated with the chimera." (PMID 31024556, 2019). "No changes were observed in the levels of the anti-inflammatory cytokines (IL-10 and IL-13) and the pro-inflammatory cytokines TNF-α in brain homogenates of WT and MBL-null mice after infection with HSV-1." (PMID 31869396, 2019). "Before infection, 7% (IQR, 3%–12%) of CD16+ DCs spontaneously produced IL-10, IL-12, or TNF ex vivo, with TNF (5% [IQR, 4%–10%]) dominating the response." (PMID 30239833, 2019). "We profiled production of three key cytokines, TNFα, IL12, and IL8, in monocytes and DC subsets before and at 3, 6, and 12 weeks after infection." (PMID 31736945, 2019). "The other cytokine such as IL-6, TNFα, response to early febrile and defervescence phases of DENV-infection varied significantly and even led to contradictory conclusions." (PMID 31877138, 2019). "Similar to WT mice, in the CNS of Rag1−/− mice IFN-α1, IFN-β, TNF, IL-1α, IL-1β, IL-6, and IFN-γ mRNA levels increased following i.c. infection with ZIKV, and IL-2, IL-3, IL-4, and IL-5 mRNA was not detectable (data not shown)." (PMID 31511023, 2019). "Herein, a single unilateral injection of EcoHIV (1 × 106 pg) directly into the caudate putamen resulted in a significant increase in inflammatory markers TNFα, IL-1β, IFNγ, CCL2, CCL3 and CXCL10 5 days after infection." (PMID 31263138, 2019). "Organs were harvested at day 3 and 5 of infection and total RNA was isolated and amplified for the mRNA of the housekeeping gene, HPRT, and the cytokines TNF, IL-6, IL-12 and IL-10." (PMID 31242184, 2019).
infection (continued). "Treatment of WT‐derived BMMCs led to significantly elevated levels of IL‐6, TNF‐α, KC, MIP‐2 and CRAMP in KitW-sh/W-sh mice upon infection." (PMID 30729611, 2019). "Tumor necrosis factor (TNF) is a central regulator of macrophage pro-inflammatory phenotypes during homeostasis, inflammation, and infection." (PMID 31611882, 2019). "For cytokines, in the ileal mucosa, AH02LA infection markedly up-regulated (p < 0.05) gene expression of IL-1β, IFN-γ, and TNF-α." (PMID 31195631, 2019). "The protein levels of interleukin (IL)-1α, TNFα, MIG (CXCL9), and IP-10 (CXCL10) were significantly higher in ZBP1−/− mice compared to the WT mice at day 2 after infection." (PMID 31572318, 2019). "As shown, both TNFAIP3-KO cell clones (KO#20 and KO#03) showed significant higher levels of proinflammatory factors like TNF-α, IL-6, IL-1β, and CCL2 in response to the infection, as compared to that of the wild-type cells." (PMID 31783671, 2019). "After high-dose infection (5 × 106 CFU per mouse), bronchoalveolar lavage fluid (BALF) TNF levels recovered at 2 h and IL-1β and IL-6 at 4 h were higher in response to the TIGR4 strain compared to infection with the TIGR4 Δcps strain." (PMID 31551336, 2019). "Secretion of 11 cytokines was analyzed after 72 h of infection and significant differences with regard to secretion of IFN-γ, TNF, and MIP-1β was observed between immune and naïve individuals for LVS-infected cultures." (PMID 29468144, 2018). "We then assessed the post-infection cellular responses in all Lagos study participants by LFn fusion protein stimulation of PBMCs in IFN-γ and TNF-α ELISPOTs." (PMID 29795572, 2018). "Infection with the ΔgliP mutant significantly stimulated the expression of CXCL2, CCL3, CCL4, CCL7, TNF-α, and IL-6, whereas infection with the Δaspf1 ΔgliP double mutant significantly decreased the expression of CXCL2, CCL7, TNF-α, and IL-6." (PMID 30052103, 2018). "In the present study, the experimental infection produced an increase in the pro-inflammatory cytokines IFN-γ and TNF-α in the ileum of both GN-CS and GN-PS groups when compared to GF and GN-CP groups." (PMID 30564201, 2018). "In contrast, two cytokines – TNF and IL3 – exhibited significantly higher levels in C57BL/6NJ mice on day 9 post-infection." (PMID 30713529, 2018). "It rapidly initiates a cascade of events characterized by the production of the early pro-inflammatory cytokines, IL-15, and IFN-α, quickly followed by the more sustained TNF-α and monocyte chemoattractant protein (MCP)-1 during infection." (PMID 30568659, 2018). "This increase was reduced in GN-PS group, with statistical difference (P < 0.05) from the second day of infection for IFN-γ and only on the eighth day for TNF-α." (PMID 30564201, 2018). "At 24h-post infection the concentration of MCP-1, TNFα, IFNγ and IL-12p70 and were all significantly reduced in NKLAM-KO lungs compared to WT lungs." (PMID 29518136, 2018). "Mice genetically deficient of IL-17RA or IL-23 showed increased mortality due to a shift to a Th1 profile after infection and augmented IFN-γ and TNF-α levels in the heart." (PMID 30559742, 2018). "Second, the initial levels of upregulation of TNF produced in response to AF2122 and G18 infection were similar, but at 24 hpi there was a spike in production in AF2122-infected cells." (PMID 29263113, 2018). "More recently, the parasite burden and levels of IFN-γ, TNF-α, IL-10, and TGF-β were evaluated in 5 target tissues at 6 and 16 months after infection with L. infantum in an experimental canine model." (PMID 30175073, 2018). "Accordingly, in kidney, TNFα, IL6 and IL‐1β mRNA levels were significantly reduced in p38γ/δ−/− and LysM‐p38γ/δ−/− mice at day 1 post‐infection, compared to WT mice." (PMID 29661910, 2018). "At 4 months after infection (T2), the dogs immunized with either salivary protein presented higher levels of IFN-γ, IL-6, IL-18, GM-CSF, IL-7, IL-15, TNF, and CCL2 when compared to controls." (PMID 30519235, 2018).
infection (continued). "Upon infection with BCG, we found a robust production of TNF-α (14820.02 ± 165.82 pg/ml), whose level was remarkably reduced with HDL treatment." (PMID 29712918, 2018). "Similar to infection with BCG, we found a high level of TNF-α production upon M. tuberculosis infection (9057.91 ± 219.07 pg/ml)." (PMID 29712918, 2018). "IFN-alpha (IFN-α) was detected in the lungs of 6:2 Tky/05 virus-infected mice along with IL-6 at day 2, whereas levels of TNF-α, CXCL1, CCL2 and IFN-γ continued to rise through day 3 post infection." (PMID 29300777, 2018). "As for TNFα, the levels of this cytokine were low in the REF group and the infection with either SA11 or EDIM alone induced an increase of up to four times (p < 0.05)." (PMID 29942312, 2018). "Increased levels of TNF-α, IFN-γ, IL-12, IL-23 and IL-17 was concomitant with reduced levels of TGF-β and IL-35 at both periods of infection assayed." (PMID 30410119, 2018). "Concentrations of inflammatory and immunomodulatory cytokines IL-1β, IL-6, TNF-α, IL-10, and IL-13 were significantly greater in BAL samples of Nrf2 KO mice compared to WT controls at day 1 after infection (p < 0.05)." (PMID 29740449, 2018). "And infection of macrophages with the three ΔsurA/SCV1, Δslp/SCV1, and ΔlpoB/SCV1 mutants led to significantly decreased expression of TLR2, TNF-α, IL-1β, and IL-6 compared with those detected in the SCVs." (PMID 29594069, 2018). "In this regard, it is interesting that previous data showed that in HIV patients there is an infection of Kupffer cells in the liver which enhanced LPS cell-surface receptors (TLR4) and increased IL-6 and TNF-a expression." (PMID 29434676, 2018). "In this study we observed a significant increase in the concentration of all three inflammatory cytokines (TNF-α, IFN-γ, IL-6) in the supernatants of PBMCs infected with Mtb H37Ra compared to uninfected PBMCs at 3 days post-infection." (PMID 30204787, 2018). "Despite the observation from the other cytokines production, the secretions of both the TNF-α and VEGF trends increased over time after 24, 48, and 120 h post-infection." (PMID 29515555, 2018). "The effect of infection on the drug metabolizing enzymes is carried by the few cytokines such as IL-1β, IL6, tumor necrosis factor alpha (TNF-α), and interferon (INF) α or γ." (PMID 29849489, 2018). "We showed that infection of pigs with an epidemic or endemic VSV induced disparate serum levels of IgM/IgG antibodies, systemic antiviral activity, TNF and IL-6 during the acute phase, as well as marked differences in virulence." (PMID 30158915, 2018). "In early stage infection, TLR3-/- mice showed a diminished synthesis of IFN-β, IL-1β, and IL-6, but enhanced production of IL-10, TNF-α, and IFN-γ." (PMID 29624589, 2018). "Previous studies showed that interleukin (IL)-12, IFN-γ, tumor necrosis factor (TNF), inducible or type 2 nitric oxide synthase [iNOS (NOS2)], and CD4+ type 1 T helper (Th1) cells are essential for overcoming an infection with L. major." (PMID 29459858, 2018). "Their results showed that serum levels of TNF-α and IFN-α were correlated with hyperthermia, while BALF levels of IL-1β or IL-8 were strongly correlated to clinical score in the Lena-infection group." (PMID 30469357, 2018). "In both infections, we observed an increase in IFN‐γ, TNF‐α, IL‐6, IL‐8, IL‐10, IL‐13, MIP1β, and G‐CSF levels." (PMID 29314720, 2018). "Although mRNA levels of all these cytokines reduced in RV-infected mice with COPD phenotype, the levels of CXCL-1, CXCL-10, CCL3, TNF-α, IL-17A and IFN-γ remained high up to 14 days post-infection." (PMID 29975735, 2018). "And infection of macrophages with the three ΔsurA/SCV1, Δslp/SCV1, and ΔlpoB/SCV1 mutants led to significantly decreased expression of TLR2, TNF-α, IL-1β, and IL-6 compared to those detected in the SCVs." (PMID 29594069, 2018).
infection (continued). "Infection leads to Toll-like receptor (TLR) activation, production of inflammatory cytokines such as IL-6, IL-1β, TNF-α, CCL2, IFN-γ, and IL-17, and neutrophil and macrophage recruitment." (PMID 30487793, 2018). "TNF levels in the serum and TNF −308 genotype association - As expected, TNF levels in the serum were increased in T. cruzi-infected patients compared with those in non-infected controls putatively exposed to infection and born and residing in the same endemic areas." (PMID 29768622, 2018). "Increased levels of D-dimer, IL-6, sCD14, CXCL10, TNF-α, IL-18, and CCL2 among others have been shown to be increased during acute infection or chronically increased throughout infection." (PMID 29391069, 2018). "Fibroblasts infected with the HCMV strain AD169 express high levels of gB already 3 days after infection and T cells in co-culture start secreting IFN-γ and TNF upon addition of a gB specific BiTE antibody construct." (PMID 30487534, 2018). "SCRV treatment increased TNFα, IL1β, and IL8 expression at 12 h post-infection in the IRF3 knockdown cells as compared with the control cells." (PMID 29755465, 2018). "CD4+ T cells isolated from the lungs of Nlrc3-/- mice showed stronger expression of intracellular IFN-γ, TNF-α and IL-17A after restimulation than that showed by CD4+ T cells isolated from lungs of WT mice at 3 weeks post-infection (w.p.i.)." (PMID 30133544, 2018). "Cytokines, especially tumor necrosis factor α (TNF-α), interleukin 1 β (IL-1β), and interleukin 6 (IL-6), are invoked within the immune system in response to surgical stress and infection." (PMID 30405319, 2018). "On day 25-post infection, both the absolute numbers of GP33 and NP396 tetramer positive T cells were similar, while the frequencies of IFN-γ and TNF-α producing cells were lower." (PMID 29672594, 2018). "The MDR-Mtb infection of macaques appears to elicit more apparent innate-like effector responses of TNF-α-producing CD3 lymphocytes and IFN-γ-producing Vγ2Vδ2 T cells than infection with the control Erdman strain." (PMID 30538219, 2018). "Plasma levels of TNF-α, IFN-γ, IL-6, IL-10, CXCL10, CCL2 and IL-4 were all increased upon infection." (PMID 30375380, 2018). "Supernatants from cultured macrophages treated with antagomir-HA-3p had lower concentrations of TNF-α, IL-6 and IFN-β than those treated with the control antagomir at 24 and 48 h post-infection." (PMID 29327729, 2018). "TNF-α and IFN-γ are inflammatory cytokines and the latter plays an important role in the resistance to infection by Shigella in the mouse model." (PMID 29534721, 2018). "Previous single nucleotide polymorphism (SNP) studies have shown that over- or underexpression of immunoinflammatory genes such as TNF-α, interleukin- (IL-) 1, IL-10, IL-8, interferon gamma, and CD14 receptor is related to infection development in hospitals." (PMID 29950924, 2018). "We thus compared the production of IL-1β, IL-17, TNF-α and IL-10 to the number of CFU in the lungs at 96 hours post-infection for each animal." (PMID 29381692, 2018). "In contrast, accumulation of LTB4 enhanced TNF-α expression and enabled macrophage control of infection, but an excess of TNF-α results in the necrosis of macrophages and a higher burden of infection." (PMID 29472920, 2018). "All transfected cells except “mock” were followed by induction of the IFN-β promoter, either with Newcastle disease virus-infection (MOI = 3) or treatment with recombinant human TNF-α (50 ng/ml)." (PMID 29623073, 2018). "The ACT-SURE study reported 5.1 serious infections per 100 PYs following TCZ treatment in 1680 patients with RA, which is similar to the rate previously observed for the anti-TNFα antibody adalimumab." (PMID 30423923, 2018). "In the initial stages of infection by M. bovis BCG, pretreated with properdin, during phagocytosis, the expression of TNF-α was significantly enhanced." (PMID 29867915, 2018).